IL10 (interleukin 10)
Diseases named in the same sentence as IL10 in open-access papers (continued):
Sharing a sentence is not in itself a finding about the gene and the disease.
peritonitis (continued). "As expected, CLP-induced peritonitis was associated with strong systemic and local upregulation of pro-inflammatory cytokines IL-6, CCL2, and TNF as well as upregulation of anti-inflammatory IL-10 compared to sham animals." (PMID 38562925, 2024). "C. latifolia reduced TNF-α and IL-10 levels in zymosan-induced peritonitis." (PMID 27088973, 2016). "Since IL-10 is considered an anti-inflammatory mediator, our findings corroborate the fact that both pro- and anti-inflammatory mediators are produced simultaneously in the peritoneum of patients with peritonitis." (PMID 24028733, 2013). "The differences in the type and severity of injury (with a survival rate in wildtype mice of 40% in our study, but 0% in the peritonitis model), or the involvement of other mediators such as IL-10 (which is increased in knockout mice) may explain these discrepancies." (PMID 22768176, 2012). "However, IL-10 levels in peritoneal effluent were higher during peritonitis." (PMID 22481867, 2012). "Oral administration of LPE has been shown to attenuate peritonitis by reducing pro-inflammatory mediators (IL-1β, IL-6, and TNF-α) and increasing IL-10 secretion." (PMID 40079578, 2025). "In combination with visible peritonitis after the induction of surgery and reproducibly high IL6, IL-10 and TNF-alpha levels in previous studies with the same model, an abdominal infection of the animals is reliably detected." (PMID 39273258, 2024). "The oral treatment of acute peritonitis with HEVe reduced the total leukocytes, neutrophils, TNF-α, and IL-1β and elevated IL-10 levels." (PMID 39452085, 2024). "The serum levels of TNF-α, IL-1β, IL-6, and IL-10 in rats with systemic inflammation, and the levels of TNF-α in a model of acute peritonitis in rats were also investigated." (PMID 37103384, 2023). "Similarly, in mammals, during zymosan-induced peritonitis, E2 treatment promoted an anti-inflammatory and pro-resolving phenotype in zymosan-induced peritoneal macrophages, which correlated with the induction of genes involved in macrophage alternative activation and with IL-10 expression in vivo." (PMID 32519008, 2020). "In the acute peritonitis mouse model, MCL reduced the secretion of IL-6, TNF-α, IL-1β, MCP-1, IFN-β and IL-10 in sera, and ameliorated lung and liver damage." (PMID 26984741, 2016). "Of note, mice submitted to carrageenan-induced peritonitis exhibited increased IL-1β and TNF-α levels, in contrast to reduced IL-10 levels in peritoneal fluid." (PMID 21799673, 2011). "The animals with LPS-induced peritonitis did not demonstrate a significant difference in the determination of the anti-inflammatory cytokine IL-10 compared to the naive group." (PMID 39452085, 2024). "To confirm the inhibitory effects of endogenous AIM on the inflammasome activation in vivo, we used a model of LPS-induced acute peritonitis in AIM−/− and WT mice and investigated first whether AIM mediates anti-inflammatory effects of IL-10." (PMID 33414479, 2021). "Using adoptive transfer of SOCS3-silenced macrophages in a mouse peritonitis model, the investigators demonstrated that SOCS3 drives the production of M1-induced cytokines (TNF-α, IL-1β), while reducing the expression of M2-induced IL-10." (PMID 34339354, 2021). "Finally, we determined the in vivo role of AIM in the inhibitory effects of IL-10 on inflammatory responses and NLRP3 inflammasome activation in lipopolysaccharide (LPS)-induced acute peritonitis using wild type (WT) and AIM−/− mice." (PMID 33414479, 2021). "Notably, in self-limited peritonitis, RvD1 reduced PDCD4 and increased IL-10 production, providing in vivo correlates of RvD1-miR-dependent gene regulations." (PMID 23093949, 2012). "However, DEXA reduced the pro-inflammatory cytokines (IL-1β and TNF-α) but did not increase IL-10 levels in peritoneal fluid of mice with peritonitis." (PMID 21799673, 2011).
peritonitis (continued). "FTA significantly alleviated peritonitis as evidenced by the decreased number of neutrophils and levels of tumor necrosis factor alpha (TNF-α), interleukin-6 (IL-6), and monocyte chemoattractant protein-1 (MCP-1) in the peritoneal cavity, without interfering with interleukin-10 (IL-10)." (PMID 29509714, 2018).
Shock (36 papers, 2005 to 2025). The state in which profound and widespread reduction of effective tissue perfusion leads first to reversible, and then if prolonged, to irreversible cellular injury. "Although IL-10 shows an inhibitory effect on the production of most pro-inflammatory cytokines, increased IL-10 blood levels has been associated with the development of organ failure in septic shock." (PMID 36261775, 2022). "For more comprehensive results, we also measured a potent anti-inflammatory cytokine IL-10, the deficiency is thought to augment acute lung injury following hemorrhagic shock." (PMID 29948507, 2019). "The concentration of IL-10 in patients with septic shock is associated with poor clinical outcomes." (PMID 38137809, 2023). "Elevated IL-10 independently predicted septic shock (OR = 4.28, 95% CI: 2.56–7.15; p < 0.001) and identified 87% of shock cases among bacteremic patients." (PMID 40647525, 2025). "Plasma IL-10 is known to be increased in septic shock and contributes to the dysfunction of innate immunity." (PMID 24956170, 2014). "Nonetheless, further studies are required to elucidate the complex immunomodulatory action of IL-10 under the condition of hemorrhagic shock." (PMID 22046081, 2012). "High levels of IL-10 in patients with septic shock have been correlated with poor prognosis." (PMID 30609860, 2019). "The period of septic shock onset and progression was marked by progressive decline in IL-6 and MIP-2, and progressive increase in TNF-α and IL-10." (PMID 41155249, 2025). "Also, in human patients with meningococcal septic shock, it was found that IL-10 was responsible for the main monocyte inhibiting characteristics in the circulation, which reinforces the hypothesis on the anti-inflammatory role of IL-10 during clinical bacterial infections." (PMID 35464430, 2022). "We documented the early time course evolution of circulatory Prdx1, hypoxic marker carbonic anhydrase IX, inflammatory cytokines including IL-6, IL-8, IL-10, MCP-1, TNF-α, IL-1β, and danger signaling receptors (TLR4 and CD14) in a cohort of cardiogenic shock patients within 1 day after ECMO support." (PMID 27142532, 2016). "Once bacterial dose and infusion-rate optimization was achieved, all sheep developed septic shock (as per Sepsis 3 criteria) within 12 h of completion of E. coli infusion, with corresponding increases in the vasopressor requirement (VDI) and cytokines (IL-6, IL-8, IL-10, and VEGFA)." (PMID 39467921, 2024). "Finally, patients who developed septic shock showed altered immune status compared to patients who did not develop septic shock, with sustained low HLA-DR/monocytes from D2 to D28 and high serum levels of IL-6, IL-10, and IL-17 at late time points." (PMID 33737924, 2021). "Moreover, patients with NSTI and septic shock at baseline had significantly higher levels of IL-1β, IL-6, IL-10 and TNF-α level than in patients with NSTI without shock." (PMID 28176831, 2017).
Immunodeficiency (35 papers, 2006 to 2025). Failure of the immune system to protect the body adequately from infection, due to the absence or insufficiency of some component process or substance. "Differences in IL-10 expression or function have been implicated in various immunological disorders, such as immunodeficiency, chronic inflammation, or cancer progression." (PMID 38397895, 2024). "The levels of lysozyme, interleukin (IL)-2, IL-10, and IgA in blood serum at this age were minimal; starting from 28 days of age, there is a specific humoral immune deficiency, which is compensated by strengthening of cellular defense factors." (PMID 38911092, 2024). "Mutations in the genes coding for IL-10 and IL-10 receptor both present very early in life, as seen in mucosal abnormalities and immunodeficiencies, and exhibit the bowel phenotype characteristic of defective neutrophil function." (PMID 28105308, 2016). "Instead, significantly high levels of the dual target sIL-2R and IL-10 are biomarker of immune deficiency and treatment failure." (PMID 22235223, 2011). "Instead, significantly high levels of the dual target sIL-2R/IL-10 are biomarker of immune deficiency and treatment failure." (PMID 22235223, 2011). "There are not references in the bibliography reporting that an alteration of IL-10 levels could eventually cause an immunodeficiency." (PMID 16803619, 2006). "One patient was confirmed to have IL-10 receptor A (IL-10 RA) defect; one patient had comorbidity of immunodeficiency." (PMID 39850808, 2025). "By contrast, immunosuppressive cytokines such as IL-4, IL-10 and TGF-β produced by M2 macrophages are associated with immunodeficiency and the persistence and advanced infection with pathogens including MTB." (PMID 35420971, 2022). "For example, studies of participants with 22q11.2 deletion syndrome (22q11.2DS) (a neurogenetic disorder whose phenotype includes both immunodeficiency and ID/psychotic disorder) found higher levels of inflammatory markers (C-reactive protein, IL-6, IL-10, TNFα) compared with healthy individuals." (PMID 40869088, 2025). "Of interest, the low expression of CXCR4 as well as the class-A1 Rhodopsin-like receptors in COVID-derived CD4+ naïve T cells resulted in a reduced responsiveness of the IL-10 signaling pathway, which may contribute to immunodeficiency in patients." (PMID 34944610, 2021). "We conclude that the capacity of CLL cells to produce IL-10 is mediated by the CXCL12–CXCR4–STAT3 pathway and likely contributes to immunodeficiency in patients." (PMID 29379494, 2017). "In the majority of the IL-10-DLI treated patients relapse or infections occurred prior to or in time proximity with the infusion, when immunodeficiency was still severe." (PMID 24550909, 2014). "Patients with deleterious IL10/IL10R mutations are generally not more susceptible to infections, but are still considered to have an immunodeficiency." (PMID 32117262, 2020). "Here, we report that the capacity of CLL to produce IL-10 is regulated by the CXCL12–CXCR4–STAT3 pathway and may contribute to immunodeficiency in patients." (PMID 29379494, 2017). "The molecular cause for the selectively impaired production of IL-21, IL-4, and IL-10 is not understood yet, but the high expression of PD-1, a negative regulator of T cell activation might interfere with cytokine secretion and contribute to the immunodeficiency." (PMID 29375547, 2017).
Miscarriage (35 papers, 2012 to 2026). A pregnancy that ends at a stage in which the fetus is incapable of surviving on its own, defined as the spontaneous loss of a fetus before the 22th week of pregnancy. "The strongly decreased TGFß and IL10 plasma levels indicate deficient down-regulation and reflect a dysbalance of the immune system in patients with idiopathic recurrent miscarriage." (PMID 30832584, 2019). "Chi-squared test results showed that SNPs in TLR9 and IL-10 genes have statistically significant effect on the risk of miscarriage with highest of all genes' ORs of 13.23 and 12.86, respectively, for double-mutant genotypes." (PMID 30116270, 2018). "In addition, according to the literature data, the reduced production of IL-10 and IFNγ cytokines in the decidua is associated with miscarriage." (PMID 40332223, 2025). "Indeed, women with recurrent spontaneous miscarriage show elevated Th17 responses, a decidual IL-10 deficiency, and extensive local inflammation." (PMID 38107518, 2023). "Our data provide further evidence to the hypothesis that IL-10 SNPs that result in decreased IL-10 production lead to increased risk of miscarriage." (PMID 30116270, 2018). "Furthermore, some authors have reported spontaneous abortion cases and patients with recurrent miscarriage are associated with lower systemic IL-10 compared to normal pregnancies." (PMID 30539027, 2018). "IL-2/IFN-γ and IL-4/IL-10 are secreted by Th1 and Th2 lymphocytes, respectively; therefore, the results from the previous studies support a shift from Th1 to Th2 signaling events during implantation; and preventing this shift is associated with miscarriage." (PMID 24926365, 2014). "B cells in the abdominal cavity mediate immune tolerance via IL-10 production and prevent miscarriage during pregnancy." (PMID 35371051, 2022). "In agreement with a previous study, the results showed increased IL-2 (p < 0.05) and decreased IL-10 level in the embryonic miscarriage group compared with control." (PMID 33299847, 2020). "MDC1 from miscarriage patients had a significant reduced capacity to secrete IL-1β, IL-6, IL-10, and TNF, while MDC2 from miscarriage patients did not behave differentially from MDC2 of normal pregnant women." (PMID 31681319, 2019). "TLR2, TLR4, IL-6, IL-8, and PGR SNPs can also affect the risk of miscarriage, but in less extent than TLR9 and IL-10." (PMID 30116270, 2018). "The following triple genetic interaction showed statistically significant association with the risk of miscarriage: TLR9, IL-10, and TLR4." (PMID 30116270, 2018). "The following double genetic interactions showed statistically significant association with the risk of miscarriage: TLR9 and IL-6; TLR9 and IL-8; TLR9 and IL-10; and IL-10 and TLR4." (PMID 30116270, 2018). "TLR9 AA, IL-10 AA, and TLR4 CC interaction (z = 44.826, p < 0.001) and TLR9 GG, IL-10 CA, and TLR4 CT interaction (z = 44.826, p < 0.001) had a statistically significant positive effect on the risk of miscarriage." (PMID 30116270, 2018). "Mutant SNPs in TLR9, IL-10, TLR2, IL-6, and IL-8 genes were found to have statistically significant effect on the risk of miscarriage with help of multiple logistic regression." (PMID 30116270, 2018). "The multiple logistic regression analysis has also shown that the following double interactions showed statistically significant association with the risk of miscarriage: TLR9 and IL-10; TLR9 and IL-8; TLR9 and IL-6; and IL-10 and TLR4." (PMID 30116270, 2018). "TNF -238G > A, TNF -308G > A, IL1B -511 T > C, IL1B 3954C > T, IL6 -174G > C, IL6 -634C > G, IL10 -1082A > G and IFNG 874A > T polymorphisms were genotyped on 775 women with idiopathic recurrent miscarriage and 805 healthy parous control women." (PMID 29017513, 2017). "In the field of reproductive immunology in a set-up similar to our study, an intronic haplotype was found to result in IL-10 secretion changes in women with idiopathic recurrent miscarriage." (PMID 28611769, 2017).
Miscarriage (continued). "They induce miscarriage in mice, which can be reversed by inhibitors of the Th1 cytokines or by administering the anti-inflammatory IL-10 and Th2 cytokine IL-4." (PMID 26335138, 2015). "In the present study, we also found that in early pregnancy (i.e., before 14 weeks), the amount of TNFα and IL-10 secreted in vitro by villous tissue from sporadic miscarriage was lower in the group with a normal karyotype." (PMID 21977049, 2012). "Yet, the profiles from day ET+16 indicated a significant difference concerning an increase of the pro-inflammatory cytokines IL-17, IFN-γ and TNF-α in the miscarriage group, but a sustained increase of anti-inflammatory cytokines IL-10 and TGF-β1 in the live birth group." (PMID 37744353, 2023). "Furthermore, women who have embryonic miscarriages exhibit higher vaginal levels of interleukin 2 (IL-2) and lower levels of interleukin 10 (IL-10) than control subjects." (PMID 35265534, 2022). "In our work, it was true that no statistical differences in serum Il-6 concentration were found in the study and control group, but in correlation with Il-10 it was found that in missed miscarriage, the increase in Il-10 concentration was followed by a significant increase in Il-6 concentration." (PMID 34444287, 2021). "Genetic susceptibility may be involved in the onset of recurrent miscarriage and play an important role in the occurrence and development of RM 30; such genes include FOXP3, IL‐10, and TNF‐α." (PMID 31454102, 2019). "TLR9 GG and IL-10 CC interaction (z = −3.418, p=0.0006) and TLR9 GG and IL-10 CA interaction (z = −3.094, p=0.0019) had a statistically significant negative effect on the risk of miscarriage." (PMID 30116270, 2018). "Moreover, one triple genetic interaction was significantly associated with the risk of miscarriage: TLR9, IL-10, and TLR4." (PMID 30116270, 2018). "Moreover, in normal pregnancy, Tim-3+PD-1+ CD8+ T cells, the number of which was more than that in miscarriage, produced higher levels of IL-4 and IL-10 but lower levels of IFN-γ and TNF-α." (PMID 25950468, 2015). "In cases of miscarriage, the expression of B7-2 was found to be highly upregulated at the fetomaternal interface and this was associated with high levels of Th1 cytokines (IL-2 and IFN-gamma) and low levels of Th2 cytokines (IL-4 and IL-10)." (PMID 25189405, 2014). "It was found that the endometrial expressions of proinflammatory cytokines such as TNF-α were up-regulated and interleukin-10 (IL-10), as an important anti-inflammatory cytokine in pregnancy, was down-regulated in idiopathic recurrent spontaneous miscarriage women." (PMID 25709630, 2014). "In addition IL1 β, IL-6, IL-10 and CXCL8 (IL-8) have previously been examined in maternal circulation in association with miscarriage." (PMID 24699265, 2014). "A previous study reported a reduction in IL-10, Tim-3, or LILRB4 expression in dMφ in a mouse model of T. gondii-induced miscarriage." (PMID 38987795, 2024). "Our results showed that the level of IL2 was higher, whereas IL10 was lower in the embryonic miscarriage group than the control group, suggesting IL2 is dominant than IL10 that resulted in immune system depression in the embryonic miscarriage group." (PMID 33299847, 2020). "In conclusion, we have found plasma concentrations of the cytokines IL-1β, IL-6 and IL-10, and the chemokines, CXCL8, CCL2, CCL5, CCL7, CX3CL1 cannot predict subsequent miscarriage." (PMID 24699265, 2014). "Stimulation of PBMC from women with recurrent miscarriage with P4 did not modify the secretion profile of IL-10." (PMID 26446923, 2015). "The increase in activating isoforms did not correlate with higher expression of TNF-α, IFN-γ, IL-10, and placental growth factor mRNAs in the placental tissue of those women who experienced sporadic miscarriage, as compared to those that had undergone elective abortions." (PMID 28424697, 2017).